CD4 (CD4 molecule)
Diseases named in the same sentence as CD4 in open-access papers (continued):
Sharing a sentence is not in itself a finding about the gene and the disease.
tumor (continued). "For instance, BI1361849, as an mRNA encoding non‐small cell‐associated tumor antigens, can promote the proliferation of functional tumor‐specific CD4 and CD8 cell, killing the cancer cell and improving survival." (PMID 37206219, 2023). "Numerous studies including our study investigated CD8+ and CD4+ to detect lymphocytes trafficking to the tumor to determine the association with PD-L1 expressions or with the disease prognosis, but activation status of these TILs are infrequently studied." (PMID 36604635, 2023). "Tregs, MDSCs, M2-polarised tumor-associated macrophages (TAMs) and T helper 2 (Th2) CD4+ T cells), increased expression of co-inhibitory receptors on T cells themselves (ex." (PMID 38275827, 2023). "Conventional subsets of CD4+ T cells including T helper type 1 (TH1), TH2, TH17, TH9, T follicular helper (TFH) and Tregs are found within tumours and numbers of CD4+ T cells with TH1 phenotype are associated with beneficial outcomes." (PMID 37190281, 2023). "Collectively, these results showed that RNase1 contributed to a significant induction of CD4+ Th1, CD4+ Th17, and NK cells, which associate with antitumor immunity, as well as a reduction of immunosuppressive MDSCs that associate with pro-tumor activity." (PMID 37416781, 2023). "These mutation-specific polyfunctional Th1 type CD4+ cells gained tumor control when the ACT approach with 25% TILs was used." (PMID 38328405, 2023). "Phenotypic changes were more evident in the CD4+ compartment, which was associated with an increased proportion of CD4+ cells recovered from tumours compared to the CD4+/CD8+ ratio at pre-injection." (PMID 37684239, 2023). "In a sporadic CRC model, targeting IL-23R in Treg cells increased IL-17 production by CD4+ T cells and increased the frequency of pro-inflammatory macrophages that was associated with decreased tumor volume and improved survival." (PMID 38375204, 2023). "By phenotyping immune cells isolated from cervical tumor brush samples, the same group also reported an association between expanded CD4+ tumor infiltrating lymphocytes (TILs), favorable response upon radiation treatment, and high microbial diversity." (PMID 36828830, 2023). "Analysis of immune cell infiltration revealed higher regulatory T cells (Tregs) (tumor-promoting cells) in the high-risk group, however, activation of M0 macrophages and memory CD4+ T cells (anti-tumor cells) activated was higher in the low-risk group." (PMID 37664030, 2023). "Different subgroups of background ICs, including tumour-associated macrophages (TAMs), were assessed and scored for CD4, CD8, FOXP3, and CD163 expression." (PMID 38175373, 2023). "We have uncovered a novel association between a higher tumor expression of IL17RB with CD4 Tem, memory B, and activated NK TS and IL17REL with CD8 Tcm, memory B, M1 macrophages and T Helper cell TS and the improved prognosis of HPV-infected HNSCC patients." (PMID 37111458, 2023). "Conventional type 1 dendritic cells (cDC1) respond to activated CD4+ T cells by generating cytotoxic T lymphocyte (CTL) responses against cell-associated tumor antigens." (PMID 37892995, 2023). "Macrophages can also act as professional APCs, delivering tumor-associated antigens to T cells to initiate the anti-tumor effect of CD4+ and CD8+ T cells." (PMID 36976060, 2023). "Protection in treatment settings was associated with the induction of tumor/Ova-specific CD4 and CD8 IFN-ɣ responses." (PMID 35173308, 2022). "Whereas, increasing monocytic MDSC subsets in the tumor retained a positive association with CD4+ T cells." (PMID 35681695, 2022). "There are also reports the ratios of tumor‐infiltrating CD4+/CD8+ are associated with the survival of the patients with HCC." (PMID 35577774, 2022). "They promote tumor growth via interactions with multiple immune cells within the carcinoma microenvironment, such as tumor-associated macrophagocytes, CD4+ and CD8+ T cells, natural killer (NK) cells, and myeloid-derived suppressor cells (MDSC)." (PMID 36211467, 2022).
tumor (continued). "In vivo, RFA also induced immunogenic modulation, and when combined with CEA-targeting vaccine, promoted tumor regression and abscopal effect, which was associated with CD4 immune responses to CEA and cascade antigens." (PMID 36497086, 2022). "Meanwhile, the expression levels of CYBB were strongly positively associated with B cells, CD8 + T cells, CD4 + T cells, macrophages, neutrophils, and DCs (P < 0.001) and were only significantly negatively associated with tumor purity level (P < 0.001)." (PMID 36253777, 2022). "The results showed that the high‐risk group was positively associated with tumor‐infiltrating immune cells, including monocytes, fibroblasts, and macrophages, but negatively related to CD4+ T cells and CD8+ T cells." (PMID 35421267, 2022). "Some of these cells have antitumoral behavior (NK cells, CD8+ T cells, CD4+ Th1 cells, and APCs), while others can promote tumor progression (CD4+ Th2 cells, regulatory T cells, and tumor-associated macrophages)." (PMID 35928965, 2022). "As a result of this stimulation, antigen-specific CD4 T cells produce IFNγ causing a phenotypical and functional switch in the TAMs, from tumor nurturing to an inflammatory M1-like phenotype." (PMID 35903540, 2022). "CD4- naïve T cells and CD4+ T cells are enriched in high-risk subtypes, indicating an immunosuppressive tumor microenvironment." (PMID 36032097, 2022). "In particular, the infiltration of cytotoxic CD8+ T lymphocytes, CD4+ T lymphocytes, and tumor-associated macrophages (TAMs) predicts favorable outcomes." (PMID 35528236, 2022). "Associated with the tumor stage are activated T cells CD4 memory, T cells follicular helper, and M1 macrophages." (PMID 35646079, 2022). "The expression of immune checkpoints including programmed cell death protein 1(PD-1), lymphocyte-activation gene 3 (LAG-3), cytotoxic T-lymphocyte-associated protein 4 (CTLA-4) on tumor-infiltrating CD4+ T cells was reduced as well." (PMID 35774793, 2022). "But the persistence of CD4 CAR T cells after removal of tumor cells can lead to aplasia of CD4 positive T cells and cause HIV/AIDS-like syndrome." (PMID 36523990, 2022). "The findings revealed that the high-risk group was positively related to tumor-infiltrating immune cells, including B cells, CD4+ T cells, CD8+ T cells, NK cells, macrophages, monocytes, and myeloid dendritic cells." (PMID 35909900, 2022). "By integrating and analyzing these results, the results revealed that the high-risk group was positively related to tumor-infiltrating immune cells such as B cells, CD4+ T cells, CD8+ T cells, NK cells, macrophages, monocytes, and myeloid dendritic cells." (PMID 35909900, 2022). "We reasoned that a higher mutation burden would increase potential tumor antigen availability to cytotoxic CD4+ and CD8+ cells." (PMID 35831288, 2022). "To determine the correlation between the risk score and tumor-infiltrating immune cells, we found that the risk score was positively correlated with B cell and CD4+ T cell and negatively correlated with Th1 and neutrophil (p<0.05)." (PMID 36203430, 2022). "A lower CD4+/CD8+ ratio at the stromal internal tumor region was significantly associated with longer distant metastasis-free survival." (PMID 35454849, 2022). "In the HPV− tumors group, miR-605-5p was associated with CD8 + T cells, activated CD4 T cells (considered tumor suppressors), and M1 macrophages." (PMID 35200568, 2022). "STAT3 blockade also can revert DC immunosuppression by inducing maturation, thus is associated with an increase in tumor infiltrating CD4+ and CD8+ T cells and a decrease in T regulatory cells." (PMID 36230990, 2022). "In lung adenocarcinoma, the EMT signature of the tumor was associated with increased infiltration by CD4+ FoxP3+ Tregs, a decreased infiltration of activated effector T cells (including Th17 cells), and higher levels of activated B cells and γδ T-cells." (PMID 35634292, 2022).
tumor (continued). "Both BAY-D and BAY-I treatments led to a significantly decreased total tumor-associated Treg numbers and the percentage of Treg in CD4+ T cells." (PMID 35013322, 2022). "In both models, Lm-LLO-CD105A demonstrated an ability to reduce the tumor-associated population of CD4+Foxp3+ Tregs in comparison with either Control Lm or PBS." (PMID 36439126, 2022). "We believe that the purity of the tumor and multiple immune cells that infiltrate tumors (DC cells, B cells, CD4+ T cells, and CD8+ T cells) were associated with AHNAK expression in BC." (PMID 35954405, 2022). "The infiltration of mucosal-associated invariant T cell (MAIT), CD8+ T cell, and CD4+ T cell in the tumor was significantly decreased in the DM-4T1 group compared with the 4T1 group." (PMID 35578660, 2022). "CIBERSORT and TIMER (immune cells infiltrating estimation analysis tools) were used to identify the relationship between activated memory CD4+ T cells and genes associated with immune infiltrating cells in the tumor microenvironment." (PMID 35711924, 2022). "Higher levels of tumor infiltrating CD4+ T cells and CD8+ T cells were associated with a significantly longer PFS (p = 0.022 and p = 0.043, respectively)." (PMID 36497475, 2022). "ECT treatment resulted in an increased percentage of CD4+ T, splenic memory B and tumour-associated dendritic cell subsets." (PMID 36551739, 2022). "In this study, the proportion of memory-activated CD4 T cells and M0 macrophages was higher in patients with high risk score, which confirmed the role of LARs in the regulation of tumor immune invasion." (PMID 35355509, 2022). "The high risk mitophagy groups had higher tumor mutation burden, stemness phenotype, total CNVs and lower CD4+ T cells infiltration." (PMID 36612054, 2022). "The presence of EGFL7 mRNA transcripts in the epithelium and/or endothelium of tumor microenvironment was associated with a lower influx of adaptive immune effectors (CD4+ and CD8+ lymphocytes) into cancer nests." (PMID 35630004, 2022). "The CuFescore was associated with tumor-infiltrating immune cells (TIICs), comprising activated dendritic cells, activated CD4 T and CD8 T cells, as well as activated B cells." (PMID 36733399, 2022). "The underlying mechanisms of these tumor antigen‐induced CD4+CD69+FOXP3− Tregs in HCC need further investigation for cancer immunotherapy." (PMID 35474948, 2022). "For instance, recent advantages have shown that CD4+ T-cells play a dominant role in anti-tumor response and are associated with response patterns of immune checkpoint therapy." (PMID 35099641, 2022). "When they compared 4T-Trap to a non-targeted TGF-β-trap, they observed that only 4T-Trap recapitulated the tumor vascular normalization and IL-4 induction in TβRII-deficient CD4+ T cells." (PMID 35577211, 2022). "In related studies, CD40-B cells transduced with tumor antigen-encoding RNA or DNA have been demonstrated to prime tumor-specific cytotoxic CD4 and CD8 T cells in vivo." (PMID 36159874, 2022). "In this context, mutation-specific CD4+ T cells were shown to infiltrate the tumor and to be required for clinical efficacy, most likely by releasing proinflammatory cytokines such as interferon-γ (IFNG) and tumor necrosis factor-α (TNFA)." (PMID 36303101, 2022). "The TIMER database was then utilized to evaluate the relationship between TGM3 expression and tumor-infiltrating immune cells, which revealed closely association with the immune infiltration of B cells, CD4+ cells, CD8+ cells, neutrophils, macrophages and DCs." (PMID 36685895, 2022). "Conversely, CD8+ T-cell deficiency, low amounts of neoantigens, and CD4+ Th2 and Treg cells are associated with tumor-permissive anergy." (PMID 36408139, 2022). "In accordance, we also observed decreased frequencies of granzyme B producing CD8+ TILs in tumor-bearing Asm-deficient mice, after CD4+ T cell depletion." (PMID 36426850, 2022).
tumor (continued). "During this phase, dendritic cells began to mature, process the tumour-associated antigens, and migrate to the tumour-draining lymph nodes to present the foreign antigen to naive CD4+ and CD8+ T cells." (PMID 35204811, 2022). "The tumor-associated CD4+ T cell clones in STIE peripheral blood have higher cytotoxic activity than the CD8+ T cell clones, but post-progressive CD8+ T cells can be observed in patients with disease progression." (PMID 35799264, 2022). "In 198 out of 457 cases of GC, the expression of KRS was higher in the tumor cells and TAIs(tumor-associated inflammatory cells), including macrophages/monocytes, CD4-positive T cells, and neutrophils, as compared to the normal tissues." (PMID 36017335, 2022). "In 4T1.2 tumors, B-MF also markedly decreased granzyme (Gr) B+ CD4+ cells, which were implicated in tumor cell killing." (PMID 36104343, 2022). "and IL16 expression was negatively correlated with miR-128-3p expression and positively associated with CD4 + T cells infiltration in 402 tumor samples from TCGA cohort." (PMID 34968167, 2022). "Emerging evidence has indicated that tumor-infiltrating immune cells (TIICs), for instance, regulatory T cells (Tregs), CD8+ T cells, CD4+ T cells, and tumor-associated macrophages (TAMs), are involved in various malignancies." (PMID 36590308, 2022). "We present the first case, to our knowledge, of a tumor that shrank in association with elevated CD4 counts." (PMID 35141174, 2022). "An advanced tumor stage was also positively associated with the number of CD4+ CD25+ FoxP3+ Tregs within the tumor." (PMID 35326519, 2022). "Although the high-risk group has a considerable proportion of resting memory CD4+ T cells, studies have shown that tumor cells can weaken T cell reactivity and antigen processing capacity, so that T cells cannot effectively control tumor growth." (PMID 35719998, 2022). "A high density of CD4+ T cells in the tumor margin appeared also to be independently associated with favorable DFS and OS." (PMID 35392957, 2022). "It has also been proposed that the tumor microenvironment can convert the effector CD4+ T cells beneficial for anti-tumor immunity into Tregs causing the additional suppression of anti-tumor immunity." (PMID 36612231, 2022). "To see if IRGPI reflected TIME status, we analyzed associations between risk scores and tumor-infiltrated immune cells (B cells, CD4+ T cells, CD8+ T cells, macrophages, neutrophils, and dendritic cells)." (PMID 36193311, 2022). "High CD4+ cells infiltrate is associated with poor prognosis because it shifted the tumor cytokine milieu towards immunosuppression, preventing immune destruction of tumor cells." (PMID 36611806, 2022). "In these experiments, Tslptg TslprKO mice were injected with either cytokine-deficient or TslprKO CD4+ T cells followed by PyMtOvatg TslprKO tumor implantation." (PMID 35657353, 2022). "The depletion of CD8+ T-cells in these mice led to the complete loss of anti-tumour response, while only partial loss was observed with CD4+ T-cell depletion." (PMID 35205769, 2022). "Molecularly, our data suggest that cognate interaction with IFNγ-producing CD4 T cells can disengage the TAMs from their tumor-associated genetic programs and divert them instead to a tumor-rejecting program." (PMID 35903540, 2022). "In contrast, high fractions of activated memory CD4 T cells and T follicular helper cells, which are known to have anti-tumor functions, were associated with good HNSCC survival." (PMID 35042463, 2022). "Still, tumors of CD4+ T cell-depleted Asm-deficient mice showed higher tumor growth rates than CD4+ T cell-depleted Asm-WT mice." (PMID 36426850, 2022). "Relative to the surrounding normal skin, BCC tumor tissues contain significantly greater numbers of Tregs, greater than 25% of tumor-associated CD4+ T cells, similar to many cancers, including human SCC." (PMID 36074574, 2022).
tumor (continued). "Matrix metalloproteinases 2 (MMP2) promotes immunosuppressive TME formation by reducing anti-tumor-associated immune cells (CD4+ and CD8+ T cells, NK cells, and CD103+ DCs) and increasing M2-like macrophages." (PMID 36185210, 2022). "These markers were used to characterize immune cells, including CD8+ T and CD4+ T cell, B cell, M1/M2 macrophage, monocyte, neutrophil, NK, tumor‐associated macrophage, and DC in STAD and COAD." (PMID 34729929, 2022). "Tumour-associated macrophages (TAM) were shown to drive this ICB resistance through PD-L1/CD80-mediated CD4+ T-cell suppression and Treg expansion." (PMID 35454848, 2022). "A later study by this same group confirmed that CD4+ T cells are activated by IL-12 treatment and help cause tumor destruction." (PMID 36159781, 2022). "It was found that IQGAP3 is associated with a variety of tumor immune cells, especially CD4 Th2 cells and MDSCs cells in almost all tumors; however, the relationship with the immune infiltration of CD4 Th1 cells is not obvious." (PMID 36164370, 2022). "HLA-DR presents tumor-associated antigens (TAA) that are recognized by CD4+ T cells, which then produce cytokines, including interleukins and interferon-γ, to suppress tumor growth." (PMID 35794593, 2022). "High densities of tumor stromal infiltrating CD4+ and CD8+ T-cells have been significantly associated with smoking status in NSCLC and other lung diseases." (PMID 36135061, 2022). "Tumor differentiation showed a significant association with increased CD4 positivity (p=0.029) while primary tumor site showed the differential presence of CD8+ (p=0.001) and NKp46+ (p=0.015) positivity, respectively." (PMID 36268020, 2022). "This combination induced the infiltration of CD8+ and CD4+ T cells into the tumor and the upregulation of gene signatures associated with the chemoattraction of myeloid cell subsets." (PMID 35163675, 2022). "Correlation analyses of tumor-infiltrating immune cells revealed that activated NK cells were negatively correlated with risk score and that M2 macrophages, activated CD4 memory T cells, and neutrophils were positively correlated with risk score." (PMID 36353555, 2022). "The number of intratumoral Treg cells is reduced in Treg-specific Cd36-deficient mice with tumor grafts, which is associated with an increased amounts of CD8+ and CD4+FoxP3- tumor-infiltrating lymphocytes (TILs) and reduced tumor growth." (PMID 36568966, 2022). "There was also increased expression of MHC-II-associated HLA genes representing potential activation of CD4, dendritic cells and M1 macrophages in Immunotype-1 tumors, which are known to be associated with a good prognosis in several tumor types." (PMID 35964339, 2022). "As Eomes is associated with both exhausted CD4 T cells and with effectors with improved anti-tumor function, interpretation of its expression in terms of clinical prognosis can be challenging." (PMID 36358898, 2022). "The results suggested associations between tumor purity (r = 0.164, p = 9.38e-03), CD4+ T cell (r = 0.263, p = 2.64e-05), neutrophils (r = 0.199, p = 1.60e-03), and myeloid dendritic cells (r = 0.162, p = 1.05e-02) by CMTM6 expression." (PMID 35174213, 2022). "The top voted and most significant tumor-infiltrating cells included cancer-associated fibroblasts (CAFs), B cells, CD4+ T cells, CD8+ T cells, natural killer (NK) cells, dendritic cells (DCs), macrophages, neutrophils, and endothelial cells." (PMID 35719408, 2022). "The results demonstrated that the pro-tumor immune cells of M2 macrophages and resting memory CD4 + T cells were found to be higher in the high-risk group, perhaps this is the reason for their poor prognosis." (PMID 35372408, 2022). "This study showed that immune cells such as memory B cells, CD4+ T memory cells, T regulatory cells, CD8+ T cells, CD4+ Th1 cells, CD4+ Th2 cells, and other microbes in tumors were implicated in tumor growth and invasion." (PMID 36405755, 2022).